TRPV4 (transient receptor potential cation channel subfamily V member 4)
Diseases named in the same sentence as TRPV4 in open-access papers (continued):
Sharing a sentence is not in itself a finding about the gene and the disease.
cancer (continued). "Therefore, TRPV4 is a double-edged sword in cancer, and its function depends on the tumor and cell type." (PMID 36619170, 2022). "The potential validity of TRPV4 agonists or antagonists in cancer therapy needs more studies." (PMID 35331296, 2022). "At the same time, TRPV4 differential expression has also been closely related to the onset and progression of many tumors, and TRPV4 may be a target for cancer diagnosis and treatment." (PMID 36160854, 2022). "Thus, the inhibition of lactic acid and TRPV4 is applicable to hypertensive patients with cancer as a means to uncover disease mechanisms and discover potential therapeutic targets." (PMID 36160854, 2022). "Interestingly, in a 3D model, TRPV4 displayed a diffuse cytoplasmic localization in three types of cancer cells, suggesting that TRPV4 localisation is very sensitive to mechanical forces." (PMID 35883510, 2022). "The follow-up research showed that TRPV4 might affect the generation of cancer by influencing gene expression or function of SH3RF3, CHFR, ZTB1, and TRAFD1." (PMID 35813831, 2022). "Moreover, tumor-associated macrophage (TAM) infiltration levels were positively correlated with TRPV4 expression in TCGA pan-cancer samples." (PMID 34262942, 2021). "Emerging evidence has indicated the critical role of TRPV4 in diverse human cancers." (PMID 34814869, 2021). "Our study explored the role of TRPV4 in TCGA pan-cancer and further highlight a potential function whereby TRPV4 may regulate TAM infiltration and tumor immunosuppressive microenvironment." (PMID 34262942, 2021). "The impact of TRPV4 on the progression of numerous cancers requires a comprehensive understanding of its role as a biomarker for patient prognosis based on its broad influence on anti-cancer drug efficacy." (PMID 34262942, 2021). "High TRPV4 expression is associated with tumor immunosuppressive status and may contribute to TAM infiltration based on TCGA data from pan-cancer samples." (PMID 34262942, 2021). "In addition, we further assessed the influence of TRPV4 on resistance of patients to anti-cancer drugs." (PMID 34262942, 2021). "GSEA based on the Reactome pathway database was used to predict pathways in which TRPV4 may be involved in pan-cancer." (PMID 34262942, 2021). "TRPV4 is not only a key player in cardiovascular system but also in cancer." (PMID 34814869, 2021). "This indicates that TRPV4 may possess both pro- and anti-angiogenic features, depending on the cancer type and genetic background or that up- or alternatively downregulation of TRPV4 impacts distinct mechanosensitive pathways." (PMID 34356643, 2021). "Based on this, it is plausible to speculate that the expression of TRPV4 (as well as the other channels) varies between patients, types and subtypes of cancer and micro- and macroenvironments." (PMID 34199609, 2021). "Given the mechanosensitive role of TRPV4 and its ubiquitous expression, it is not surprising that TRPV4 has been implicated in disease processes such as fibrosis, foreign body response, and cancer, all of which are associated with changes in tissue stiffness." (PMID 33381111, 2020). "However, due to the pleiotropic activity of TRPA1 and TRPV4, the safety profile of channel antagonism should be carefully scrutinized, particularly regarding the impact of this therapeutic strategy on cancer outcome and on the efficacy of cancer treatment." (PMID 33317522, 2020). "TRPV4 promoted cancer progression through multiple regulations." (PMID 33230171, 2020). "Links between TRPV4 and cancer have just begun to be documented." (PMID 32186440, 2020). "Our results also provide evidence that TRPV4 inhibition may have anti-metastatic effects through effects on cancer cell migration and also through reducing metastatic initiation via effects on EMT." (PMID 33322037, 2020). "Similarly, elevated levels of TRPV4 in breast, gastric, ovarian, and colon cancers correlates with increased cancer cell proliferation, invasion, and poor patient survival." (PMID 32575381, 2020).
cancer (continued). "The next set of analyses aimed to establish that TRPV4 was linked to both calcium regulation and cell migration in EC, in order to examine our hypothesis that TRPV4-related cancer progression was due to TRPV4-related calcium influx." (PMID 33230171, 2020). "We have recently shown that the mechanosensitive ion channel transient receptor vanilloid 4 (TRPV4) expression and activity is significantly reduced in tumor endothelial cells (TEC), and that activation of TRPV4 normalized the tumor vasculature and improved cancer therapy." (PMID 31921855, 2019). "Since TRPV4 can be activated at the condition of body temperature, its high expression in these cancer cells may led the intracellular calcium higher than other cells." (PMID 31235786, 2019). "Targeting TRPV4 may have inhibitory effects on tumor onset and progression, so it is a potential prognostic index and therapeutic target for malignant tumors." (PMID 31235786, 2019). "It seems that TRPV4 exhibits different expression patterns in a cancer type-dependent manner." (PMID 31189890, 2019). "Its abnormal expression has also been closely related to the onset and progression of multiple tumors, so TRPV4 may be a target for cancer diagnosis and treatment." (PMID 31235786, 2019). "We studied the possible role of TRPV1 and TRPV4 in transducing cancer-induced hyperalgesia." (PMID 29637027, 2018). "The role of TRPV1 and TRPV4 in transducing cancer-induced hyperalgesia is investigated." (PMID 29637027, 2018). "Also, the non-cancer keratinocyte line, HaCaT, was found to be sensitive to TRPV4 activation since we observed instantaneous membrane blebbing and pyknosis, cell detachment, and necrosis." (PMID 29293584, 2018). "We have recently shown that expression and activity of mechanosensitive ion channel transient receptor potential vanilloid 4 (TRPV4) is suppressed in tumor endothelial cells and restoring TRPV4 expression or activation induces vascular normalization and improves cancer therapy." (PMID 27029071, 2016). "Taken together, these data suggest that TRPV4 regulates angiogenesis endogenously via modulation of EC mechanosensitivity through the Rho/Rho kinase pathway and can serve as a potential therapeutic target for cancer therapy." (PMID 27029071, 2016). "Indeed, our latest studies demonstrated that directly targeting TRPV4 through pharmacological activation normalizes tumor angiogenesis and improves cancer therapy in vivo." (PMID 27029071, 2016). "Thus, our current findings propose that TRPV4 can be used as an alternate therapeutic target to inhibit/normalize tumor angiogenesis via modulation of Rho/Rho kinase pathway and improve cancer therapy." (PMID 27029071, 2016). "Anti-TRPV4 antibody-drug conjugate may also be designed to target metastatic cancer cells with improved specificity and efficacy." (PMID 27291497, 2016). "Moreover, in cancer cells, TRPV4 facilitates metastatic progression by modulating actomyosin contractility and cell stiffness through Ca2+-dependent activation of the AKT–E-cadherin pathway, ultimately enhancing transendothelial migration and the invasive potential of tumor cell." (PMID 40813985, 2025). "Thus, the last group intended to clarify whether the trypsin/PAR-2/TRPV4 axis mediates cancer pain through changes in trigeminal ganglion (TG) neurons projecting to the tongue in an orofacial cancer pain model." (PMID 38730655, 2024). "In addition to research in more varied cancer pain models, an interesting approach for further studies would be to compare whether TRPV4’s amount or expression patterns are similarly distributed in males and females." (PMID 38730655, 2024). "For example, endothelial TRPV4 has been demonstrated in recent years as a key regulator of vascular integrity and tumor angiogenesis, suggesting that targeting TRPV4 may represent a potential new strategy for vascular normalization and cancer therapy." (PMID 38731434, 2024).
cancer (continued). "Thus, it should be borne in mind that the therapeutic target of TRPV4 could have effects not only on the cancer cells themselves but also on the innate response against the tumor." (PMID 37762011, 2023). "Thus, the exact role of TRPV4 in cancer and targeted drug delivery need to be investigated further." (PMID 36619170, 2022). "Furthermore, cancer cells with high TRPV4 expression are more sensitive to EGFR-targeted therapy, further suggesting that EGFR and TRPV4 expression may be functionally linked." (PMID 36497413, 2022). "While TRPV4 promotes cancer cells proliferation, migration and extravasation, activation of TRPV4 in endothelial cells suppresses vascular endothelial growth factor signaling, normalizes tumor vasculature, inhibits tumor growth and metastasis, and improves cancer therapy." (PMID 35331296, 2022). "Thus, our results indicate that both TRPV4 and t-EVs could prove to be novel targets for cancer therapies." (PMID 35004649, 2021). "Hence, dosing regimens may be critical for calcium-induced cell death in cancers that overexpress TRPV4, with maintained high levels of activator and/or combination with other agents required." (PMID 33322037, 2020). "However, other mutations outside the CaMBD domain or different mutations inside the CaMDB domains are also likely to be involved in deleterious phenotypes, as suggested by the variety of non-synonymous mutations associated with TRPV4 and TRPV6 in the COSMIC cancer database." (PMID 32186440, 2020). "Consequently, TRPV4 could be a potential therapeutic target of cancer treatment, thereby providing a new direction that develop drugs for cancer to reach the clinic." (PMID 31235786, 2019). "However, TRPV4 downregulation in cancers might be related with the differences in tumor microenvironment." (PMID 31235786, 2019). "However, whether TRPV4 is directly involved in the regulation of cancer cell proliferation, is unknown." (PMID 29293584, 2018). "TRPV4 may be an attractive molecule for both purposes as its cell surface nature provide easy access to drug target and is amenable to molecular imaging of metastatic cancer cells." (PMID 28530703, 2017). "Collectively, the data support the notion that physical “elasticity” is a potential mechanism through which TRPV4 confers metastatic potential to cancer cells – a process that may involve serverence of the plasma membrane with the cytoskeletal proteins in the cell cortex region." (PMID 27291497, 2016). "For instance, transient receptor potential cation channel subfamily V member 4 (TRPV4) activation in SCs has been shown to mediate mechanically induced pain in both in vitro and in vivo mouse cancer models." (PMID 40940747, 2025). "Recent studies have elucidated the crucial role of TRP channels, specifically TRPC3,TRPC5,TRPV4 TRPML3, in regulating the release, cargo content, and downstream effects of cancer-derived exosomes within the tumor microenvironment (TME)." (PMID 40813985, 2025). "The process of neoangiogenesis is crucial for the growth of tumors, and TRP channels such as TRPC3, TRPC6, TRPV1, TRPV4, and TRPM4 play a regulatory role in vascular permeability and cancer vascular angiogenesis." (PMID 40078961, 2025). "We evaluated the distribution of the TRP family in C1–C6 pan-cancer immune subtypes and observed that TRPC4, TRPC6, TRPM4, TRPV2, TRPV4, MCOLN1, and PKD2L1 had the potential to predict the immune subtype." (PMID 36830651, 2023). "A significant correlation was observed between TRPV4/TRPC4 and immune-activation-related genes in almost all 33 types of cancer." (PMID 36830651, 2023). "In these studies, the expression levels of TRPV4, TRPM2, TRPM4, and TRPM8 in cancer tissues are significantly increased, which is consistent with our OV research." (PMID 35813831, 2022). "TRPV4 is another TRPV channel subfamily member with well-characterized roles in cell migration and cancer metastasis." (PMID 36158191, 2022).
cancer (continued). "TRPV1 in KIRC, TRPV2 in LUSC, TRPV3 in BRCA, TRPV6 in LUAD and BRCA, while TRPV4 in KIRC and BRCA differed significantly across different cancer subtypes (P <0.05)." (PMID 35174089, 2022). "Hence, the effects of TRPV4 may be cell type- or cancer type-specific." (PMID 35331296, 2022). "As both Trpv1 and Trpv4 were expressed by MNTs, and responsive to pain inducer capsaicin, their roles in the MNT-mediated cancer pain are worth further elucidation for developing novel analgesics." (PMID 36206343, 2022). "Important signaling pathways are mediated by hedgehog (HH), Notch, wigless (Wnt), hippo (Salvador-Warts-Hippo), JAK/STAT, TRPV4, cAMP/cGMP, mTOR and platelet-derived growth factor (PDGF) for intercellular communications between cancer cells." (PMID 36498831, 2022). "Subsequently, the CNV percentage analysis in specific cancer subtypes of Hete Amp and Hete Del showed that TRPV1-6 (except for TRPV4) in KIRP, TRPV4 in ACC, TRPV6 and TRPV5 in GBM had greater than 40% Hete Amp levels." (PMID 35174089, 2022). "TRPV4 or TRPV6 is increased in endometrial, breast or prostate cancer, which promotes cancer cells metastasis." (PMID 36046433, 2021). "Moreover, there are indications that deregulation of TRPV4 could potentiate cancer invasion by affecting scattering of cancer cells: Adherens junctions seem to be regulated through TRPV4-mediated activation of Rho GTPases that induce reorganization of actin-based structures along junction formation." (PMID 34356643, 2021). "Therefore, TRPV4 might be a target for cancer diagnosis and treatment." (PMID 33230171, 2020). "Contrarily, six ion channels are overexpressed in cancers and promote the activity of Wnt pathway (TRPC5, TRPV4, TRPM4, TRPM8, P2RX7, and ASIC1a)." (PMID 33117152, 2020). "Thus, in different types of cancer TRPV4 may be either oncogenic or tumor suppressive." (PMID 31189890, 2019). "To further elucidate the ion channel function of TRPV4 in cancer metastasis, we employed Ruthenium Red (RR) and RES019–29 (RES) compound to inhibit the functions of TRPV4." (PMID 27291497, 2016). "The livers of TRPV4-KO mice exhibited fewer cancer cell microlesions, lacked macrotumors, produced lower levels of inflammatory protein S100A8, and developed fewer inflammatory cell clusters." (PMID 41100488, 2025). "However, responses to TRPV4 activation (GSK101) and inhibition (GSK219) varied across cell types, suggesting distinct roles of TRPV4 in their cancer biology." (PMID 40256993, 2025). "TRPV4 is able to regulate tumor angiogenesis and vascular maturation, so GSK1016790A has been proposed to be used together with other anticancer drugs, such as cisplatin, to achieve more effective cancer therapy." (PMID 38505262, 2024). "Regardless of the many studies conducted to unveil TRPV4’s role in cancers, the channel expression variability in different tumor tissues and the underlying mechanisms are still largely undetermined." (PMID 38730655, 2024). "Notably, we also found that several cancer-related mutation sites in RhoA, such as A3, R5, and E5453–55, are located at the interface with the TRPV4 ARD, providing evidence for an interplay between TRPV4 and RhoA in cancer, although these RhoA mutations may also impact effector binding more broadly." (PMID 37353484, 2023). "Thus, in this study, we focused on TRP channels in pan-cancer and screened two typical TRP channels, TRPV4 and TRPC4, as examples." (PMID 36830651, 2023). "Activation of TRPV4 remodels the cytoskeleton by regulating ROCK1 and promotes sc polarity via AMPK/MLC/ERM axis, thereby affecting the migration, invasion and adhesion to blood vessel of metastatic cancer cells." (PMID 37369706, 2023). "TRPV4 can affect tumor angiogenesis and inflammatory microenvironment, intervene in the cytoskeleton-related proteins including RhoA, CDC42, and Rac1, and promote cancer cells EMT." (PMID 37369706, 2023).
cancer (continued). "Regarding hypoxic TRPV4 regulation, no studies on cancer cells are present in the literature, but they are limited to other pathological states." (PMID 35806388, 2022). "This suggests that cancer has little or no influence on TRPV4-dependent global [Ca2+]i elevation in DSM cells, but impairs the mechanisms responsible for Vm depolarization and generation of electrical bursting activity." (PMID 33184390, 2020). "Although the biofunction of TRPV4 in cancers was only preliminarily explored, no previous research had examined the role of TRPV4 in cell migration or invasion in EC." (PMID 33230171, 2020). "On the contrary, activating TRPV4 with GSK1016790A can “normalize” the vascular endothelium, enhance the permeability of chemotherapeutic drugs, and ultimately reduce the exudation of cancer cells and block tumor growth." (PMID 31235786, 2019). "The decreased expression of TRPV1 and TRPV4 in cancer-bearing animals, as compared to sham, does not necessitate their decreased activity." (PMID 29637027, 2018). "Although Western blotting showed no variations in the expression of TRPV4 in normal urothelium and in low and high grade carcinomas, immunofluorescence revealed great diversity among different parts of the carcinomas." (PMID 24868547, 2014). "Finally, TRPV4 is co-expressed with different TRP channels (TRPV1 and TRPA1), and the blockage of these receptors may also reduce cancer-induced nociception." (PMID 38730655, 2024). "The diminished expression of TRPV1 and TRPV4 in cancer-bearing animals does not represent a poorly executed function but rather an interconnection between the receptor’s continuous activation by the distant invasive tumor and the increased nociception afterward." (PMID 38730655, 2024). "Taken together, our data shows that TRPV4 and calcium signal are significant sc polarity regulators in metastatic HCC, and that the pharmacological intervention that results in HCC cells becoming depolarized suggests a promising treatment for cancer metastasis." (PMID 37369706, 2023). "Unfortunately, TRPV4 regulators have not yet been used in cancer therapy clinics." (PMID 37369706, 2023). "We found that the IC50 values of several anti-cancer drugs decreased in the high-TRPV4 group, including sapitinib (an EGFR inhibitor) and selumetinib (a MEK1/2 inhibitor), indicating that patients exhibiting high TRPV4 expression levels are relatively sensitive to these anti-cancer drugs." (PMID 34262942, 2021). "Thus, inhibition of the TRPV4 seems to be predominantly (but not exclusively) favorable for cancer treatment." (PMID 32887220, 2020). "Moreover, while it has been reported to profoundly affect a variety of physiological processes, including nociception, heat sensation and inflammation, TRPV4’s role in cancer is not known." (PMID 27291497, 2016). "Therefore, this compound administration did not induce adverse effects, suggesting that TRPV4 antagonists could be a potential therapeutic target in pain conditions, such as inflammatory pain, neuropathic pain, cancer pain, and migraines." (PMID 36670886, 2022). "We found that the IC50 values of several anti-cancer drugs, including sapitinib (an EGFR inhibitor) and selumetinib (a MEK1/2 inhibitor), decreased in the high-TRPV4 group, indicating that patients exhibiting high TRPV4 expression levels may be relatively sensitive to these anti-cancer drugs." (PMID 34262942, 2021). "However, the bio-functional role of TRPV4 in cancer progression had not been examined in EC, and little was known of the specific mechanisms by which TRPV4 might act." (PMID 33230171, 2020). "However, TRPV4 does not seem to be required for cancer cell growth/proliferation." (PMID 27291497, 2016). "Thus, at the present stage, it is not possible to exclude that TRPV4 and/or TRPA1 inhibition may negatively affect cancer progression." (PMID 33317522, 2020).